CEP19 (centrosomal protein 19)
Description:
Required for ciliation. Recruits the RABL2B GTPase to the ciliary base to initiate ciliation. After specifically capturing the activated GTP-bound RABL2B, the CEP19-RABL2B complex binds intraflagellar transport (IFT) complex B from the large pool pre-docked at the base of the cilium and thus triggers its entry into the cilia. Involved in the early steps in cilia formation by recruiting the ciliary vesicles (CVs) to the distal end of the mother centriole where they fuse to initiate cilium assembly. Involved in microtubule (MT) anchoring to the centrosomes.
Synonyms: C3orf34; MGC14126; MOSPGF
Tractability: No criterion of Open Targets' tractability assessment is met for any kind of drug.
Gene: Protein-coding gene on chromosome 3 (196,706,268 to 196,712,598, reverse strand). Ensembl gene ENSG00000174007.
Subcellular location: Cytoplasm, cytoskeleton, microtubule organizing center, centrosome, centriole; Cytoplasm, cytoskeleton, spindle pole; Cytoplasm, cytoskeleton, cilium basal body
Subcellular location (Human Protein Atlas): Basal body; Centrosome; Cytosol; Nucleoplasm
Gene Ontology:
Molecular function: protein binding
Biological process: cilium assembly; microtubule anchoring at centrosome; vesicle targeting, trans-Golgi to periciliary membrane compartment
Cellular component: centriole; centrosome; ciliary basal body; cilium; spindle pole
Genetic constraint (gnomAD): Loss-of-function variants: 14 observed, 18.11 expected, observed/expected ratio (o/e) 0.77, 90% interval 0.51 to 1.21. The upper end of that interval is the gene's LOEUF score, 1.21, which puts it in group 5 of 6, group 1 being the genes least tolerant of losing a copy. Missense variants: 193 observed, 201.66 expected, observed/expected ratio (o/e) 0.96, 90% interval 0.85 to 1.08. Synonymous variants: 59 observed, 69.24 expected, observed/expected ratio (o/e) 0.85, 90% interval 0.69 to 1.06.
Homologues: Orthologues: chimpanzee CEP19 (100% identical), macaque CEP19 (97% identical), pig CEP19 (95% identical), dog CEP19 (93% identical), rabbit CEP19 (93% identical), guinea pig CEP19 (90% identical), rat Cep19 (87% identical), mouse Cep19 (85% identical), tropical clawed frog cep19 (71% identical), zebrafish cep19 (52% identical).
Diseases named in the same sentence as CEP19 in open-access papers:
CEP19 is named in the same sentence as 16 diseases in open-access papers, as found by Europe PMC text mining. Sharing a sentence is not in itself a finding about the gene and the disease. The quoted sentences say what the papers report.
Obesity (8 papers, 2014 to 2024). Accumulation of substantial excess body fat. "For example, ciliary protein centrosomal protein 19 (CEP19) was found mutated in people with obese symptom, and Cep19 knockout mice exhibited obesity, hyperphagia and other metabolic abnormalities, similar to human phenotypes." (PMID 33826123, 2022). "Additional cilia genes that are associated with obesity include CEP19, CEP290, MC4R, ADCY 3, and RPGRIP1L." (PMID 36568981, 2022). "As defects in BBS proteins are associated with obesity, and CEP19 R82* mutant patients are morbidly obese, it is possible that CEP19 cooperates with BBS proteins to form cilia." (PMID 28659385, 2017). "This work has highlighted the importance of genes in the leptin pathway (LEP, LEPR, POMC, PCSK1, MC4R) and recently homozygous stop mutations have also been identified in CEP19, encoding the cilia protein CEP19 in a large family with recessive obesity." (PMID 26132294, 2015). "The CEP19 gene encodes a 19 kDa centrosomal protein involved in obesity, glucose intolerance and insulin resistance." (PMID 25485937, 2014). "The inability of CEP19 R82* to restore ciliation in CEP19 KO cells may point to a ciliopathic explanation of how this homozygous mutation is linked to obesity." (PMID 28659385, 2017). "Knockout experiments in mice showed that the deletion of the CEP19 gene could lead to obesity in animals." (PMID 34646484, 2021). "Interestingly, a morbid-obesity-associated R82* truncated mutant of CEP19 cannot ciliate nor interact with FOP and CEP350, indicative of a putative role for CEP19 in ciliopathies." (PMID 28659385, 2017).
Infertility (2 papers, 2022 to 2024). "Among these mutated infertility genes, mutations of FSIP2, CFAP69, CEP19, MSH5 or MCM8 are recessive for spermatogenic failure or premature ovarian insufficiency." (PMID 35547809, 2022). "Alternatively, genes with no reported COI are enriched in gene sets associated with germ cell development and implicated in infertility mainly caused by spermatogenic failure (e.g., CATIP, CFAP65, CEP19) and oocyte/zygote/embryo maturation arrest (e.g., PADI6, REC114, WEE2)." (PMID 39202055, 2024).
morbid obesity (2 papers, 2017). An excess of body weight, normally defined as an individual with a body mass index greater than 35 or a body weight greater than one hundred percent of ideal body weight. "Recently, a mutation in the gene encoding for the centrosomal protein 19kDa (CEP19), a protein localized in the centrosome and in the PC, has been associated with morbid obesity in humans and mice." (PMID 28913352, 2017).
cervical cancer (1 paper, 2021). A primary or metastatic malignant neoplasm involving the cervix. "Some hotspot genes (e.g., KLF5, LRP1B, and KLF12) have previously been described in cervical cancer, and others (e.g., CADM2, CEP19, CSMD1, and NRROS) are reported for the first time in the present study." (PMID 34885212, 2021).
ciliopathies (1 paper, 2017). "It would be interesting to investigate the role of CEP19 in various tissue and organoid models, in particular the ones that are directly affected in ciliopathies, like kidney and liver." (PMID 28659385, 2017). "Together, these data demonstrate a role for the CEP19, FOP and CEP350 module in ciliogenesis and the possible effect of disrupting their functions in ciliopathies." (PMID 28659385, 2017).
Hyperglycemia (1 paper, 2020). An increased concentration of glucose in the blood. "In this study, Ephx2, Stc2, Cep19, Il15 and Fbxw7 genes were found to be associated with impaired glucose tolerance and hyperglycemia." (PMID 32095365, 2020).
melanoma (1 paper, 2020). A malignant, usually aggressive tumor composed of atypical, neoplastic melanocytes. "Most of the shared genes (40 genes) were downregulated including MMP16, IGF1R, FLOT1 and CEP19 and are functionally involved in several types of cancers, including melanoma." (PMID 32613561, 2020).
cancer (2 papers, 2020). A tumor composed of atypical neoplastic, often pleomorphic cells that invade other tissues. "Taking all these data into account, we identified the following candidates as potential causes of CA in human cancer: gain of function of CEP19, CEP72, CTNNB1, PTK2, NDRG1, SPATC1, TBCCD1; and loss of function of CEP76, MCPH1, NEURL4, NPM1." (PMID 32681070, 2020).
CEP19 also shares sentences with these, for which no sentence is quoted: Glucose intolerance (1 paper); Hypertension (1); Impaired glucose tolerance (1); Insulin resistance (1); Premature ovarian insufficiency (1); retinal degeneration (1); retinopathy (1); spermatogenic failure (1).